GPR34 (G protein-coupled receptor 34)
Diseases named in the same sentence as GPR34 in open-access papers (continued):
Sharing a sentence is not in itself a finding about the gene and the disease.
tumor (13 papers, 2020 to 2026). "Using stable GPR34 knockdown LS174T cell models, we found that GPR34 loss-of-function resulted in impaired proliferation, colony formation, and xenograft tumor growth." (PMID 34997428, 2022). "In another study, ABHD16A was suggested to generate GPR34-engaging lysoPS in the tumor microenvironment though it was unclear if AC were needed." (PMID 41212150, 2026). "In this study, we observed that GPR34 was aberrantly upregulated in ATC and the deletion of GPR34 inhibited tumor progression both in vivo and in vitro." (PMID 40862294, 2025). "The mRNA level of GPR34 was detected by RT-PCR in tumor tissues and adjacent normal tissues from 34 CRC patients." (PMID 34997428, 2022). "Based on RT-PCR results, GPR34 exhibited high level in tumor samples compared with adjacent normal samples." (PMID 34997428, 2022). "Consistent with the in vitro results, GPR34 knockdown in LS174T cells inhibited xenograft tumor growth in vivo, compared with LS174T-vector injected mice." (PMID 34997428, 2022). "GPR34 expression showed a tendency of higher expression in tumor tissues, compared with adjacent normal tissues (P = 0.083)." (PMID 34997428, 2022). "The tumor-suppressive role of miR-300 was confirmed to be mediated through GPR34 at the molecular level." (PMID 34950207, 2021). "Based on our findings, we suggest that lysoPS production from apoptotic tumor cells by stromal PLA1A may help recruit or retain cells engineered to overexpress GPR34." (PMID 41212150, 2026). "The in vivo experiment further corroborated that GPR34 suppression markedly impeded tumor growth." (PMID 40862294, 2025). "The Hom-MG-1 subgroup highly expressed the innate characteristic genes of microglia (Tmem119, P2ry12, Crybb1, Cst1, Gpr34, and Cx3cr1), poorly expressed tumor activation-related genes, and expressed early activation genes to a certain extent (Jun, Junb, Jund, and Fos)." (PMID 39867913, 2024). "In this work, the expression of GPR34 was shown significantly higher in CRC tumor samples." (PMID 34997428, 2022). "Last, we evaluated the GPR34 mRNA level of 34 CRC tumor tissue using RT-PCR." (PMID 34997428, 2022). "Similarly, our data showed that lyso-PS can activate RhoA activity via GPR34/Gi axis, which proposes a potential new molecular mechanism of lyso-PS on tumor metastasis." (PMID 33875796, 2021). "Furthermore, we identified USP8 is a novel DUB of GPR34, which could rescue the effects caused by GPR34 deletion, and targeting USP8 with DUB-IN-3 could restrain tumor growth in ATC, offering a new potential strategy for this treatment-resistant cancer." (PMID 40862294, 2025). "A recent study identified G-protein-coupled receptor 34 (GPR34) as a key immune checkpoint receptor on ILC1s that senses lysophosphatidylserine (LysoPS), a lipid enriched in the TME, primarily derived from tumor cells and infiltrating apoptotic immune cells." (PMID 40963622, 2025). "We employed stable GPR34 knockdown LS174T cell models, GPR34 Mab blocking, a CCK-8 kit, and a colony formation assay to characterize the effect of GPR34 on the proliferation of LS174T in vitro and xenograft tumor growth in vivo." (PMID 34997428, 2022). "Our findings provide direct evidence that GPR34 regulates the proliferation of LS174T cells and the growth of LS174T tumor xenografts by regulating different pathways." (PMID 34997428, 2022). "Since GPR34 expression was increased in LS174T cells, we studied the role of this signaling molecule in the context of proliferative and colony formation properties in vitro and xenograft tumor growth in vivo." (PMID 34997428, 2022). "However, GPR34 mRNA level was not significantly correlated with various clinicopathological GC parameters, including TNM stage, tumor stage, Lymphovascular invasion and distal metastasis, etc.." (PMID 34997428, 2022).
cancer (6 papers, 2021 to 2025). A tumor composed of atypical neoplastic, often pleomorphic cells that invade other tissues. "Further studies will be required to additional cancer cell lines of the colon to define the role of GPR34." (PMID 34997428, 2022). "All these findings indicate that GPR34 exerts a cancer cell specific effect on the expression of PI3K subunits through upregulating PTEN." (PMID 34997428, 2022). "In order to appraise the functional aspect of this posttranscriptional repression of GPR34 by miR-300, GPR34 was transiently downregulated in CaSki cancer cells, and GPR34 silencing was confirmed by qRT-PCR." (PMID 34950207, 2021). "It remains to be investigated whether the suppressive effect of GPR34 on ferroptosis is present in other cancer types." (PMID 40862294, 2025). "The 3′UTR stretch of GPR34 was thus cloned with wild type (WT) or mutant (MUT) miR-300 binding site to generate the respective luciferase reporter construct which was then cotransfected with miR-300 mimics or miR-NC into CaSki cancer cells." (PMID 34950207, 2021). "Similarly, the CaSki cancer cells downregulating GPR34 showed remarkably lower colony formation as that of the negative control cells." (PMID 34950207, 2021). "Therefore, this leads us to explore the carcinogenic effects of GPR34 on ATC and its specific regulatory mechanisms, and further elucidate the impact of GPR34 on cell fate, which may provide a new effective target for cancer therapy." (PMID 40862294, 2025).
neurodegenerative disease (2 papers, 2019 to 2024). A disorder of the central nervous system characterized by gradual and progressive loss of neural tissue and neurologic function. "Therefore, GPR34 is a potential therapeutic target for neurodegenerative diseases and neural injury." (PMID 30975169, 2019).
bacterial infection (1 paper, 2017). "Mice with a deficiency of G protein coupled receptor 34, the lysoPS receptor, showed less immune cell infiltration and higher levels of cytokine production upon bacterial infection than did wild-type mice." (PMID 28341849, 2017).
genetic diseases (1 paper, 2020). "Down-regulation of Fcrls and Gpr34 in MG is associated with aging and genetic diseases, and a role for these genes in MG homeostatic function has been suggested." (PMID 32831144, 2020).
neurological disorders (1 paper, 2019). "Intriguingly, P2ry13 and Gpr34, mouse orthologs of genes we identified in our human microglial gene set, are known to show down-regulation in so-called DAM that are found in AD and other neurological disorders." (PMID 31214167, 2019).
GPR34 also shares sentences with these, for which no sentence is quoted: leukemia (2 papers); autism (1); clear renal cell carcinoma (1); Cognitive impairment (1); gastric tumor (1); infection (1); melanoma (1); neurodevelopmental disorder (1).